RN7SL170P (RNA, 7SL, cytoplasmic 170, pseudogene)
Gene: Miscellaneous RNA gene on chromosome 20 (56,688,401 to 56,688,695, forward strand). Ensembl gene ENSG00000241821.
Homologues: Orthologues: chimpanzee Metazoa_SRP (97% identical), macaque Metazoa_SRP (88% identical). Paralogues in human: RN7SL1 (85% identical), RN7SL3 (84% identical), RN7SL2 (84% identical), RN7SL126P (82% identical), RN7SL220P (82% identical), RN7SL507P (81% identical), RN7SL278P (81% identical), RN7SL575P (81% identical), RN7SL732P (81% identical), RN7SL113P (80% identical), Metazoa_SRP (80% identical), RN7SL333P (80% identical), and 701 more.